CYP2B7P (cytochrome P450 family 2 subfamily B member 7, pseudogene)
Synonyms: CYP2B; formerly CYP2B7P1
Gene: Transcribed unprocessed pseudogene on chromosome 19 (40,924,273 to 40,949,234, forward strand). Ensembl gene ENSG00000256612.
Diseases named in the same sentence as CYP2B7P in open-access papers:
CYP2B7P is named in the same sentence as 6 diseases in open-access papers, as found by Europe PMC text mining. Sharing a sentence is not in itself a finding about the gene and the disease. The quoted sentences say what the papers report.
Obesity (2 papers, 2020 to 2023). Accumulation of substantial excess body fat. "For instance, target genes (FLAD1, SLFNL1, GNS, FBXL18, CYP2B7P) are commonly upregulated genes in metabolic-induced HCC and are associated with risk factors, such as diabetes, obesity, and other metabolic syndromes." (PMID 32228601, 2020).
diabetes (1 paper, 2020). "CYP2B7P was also found to be a gene target of hsa-miR-183-5p that is a biomarker of HCC and diabetes." (PMID 32228601, 2020).
lung adenocarcinoma (1 paper, 2021). A carcinoma that arises from the lung and is characterized by the presence of malignant glandular epithelial cells. "Lower expression of CYP2B7P is associated with prognosis of lung adenocarcinoma." (PMID 33931030, 2021).
nasopharyngeal carcinoma (1 paper, 2023). A carcinoma arising from the nasopharyngeal epithelium. "Overexpression of CYP2B7P impaired the migration and invasion abilities of nasopharyngeal carcinoma cell lines." (PMID 36975430, 2023). "CYP2B7P is downregulated in nasopharyngeal carcinoma, and its expression is lower in nasopharyngeal carcinoma tissues and cell lines." (PMID 36975430, 2023).
CYP2B7P also shares sentences with these, for which no sentence is quoted: metabolic syndrome (1 paper); rectal tumor (1).